RASD1 (ras related dexamethasone induced 1)
Diseases named in the same sentence as RASD1 in open-access papers (continued):
Sharing a sentence is not in itself a finding about the gene and the disease.
astrocytoma (2 papers, 2017 to 2021). "In addition, a significantly positive association of RASD1 levels with the overall survival of astrocytoma patients was found by analyzing a public database." (PMID 28600528, 2017). "Lastly, we assessed the expression of RASD1 protein levels in various grades of astrocytoma tissues." (PMID 28600528, 2017). "In the present study, by analyzing a public genomics database, we found that high levels of RASD1 predicted good survival of astrocytoma patients." (PMID 28600528, 2017). "However, we found a significant increase in RASD1 protein levels in astrocytoma tissues, especially pathological grade II and grade III tissues." (PMID 28600528, 2017). "The increased stability of farnesylated RASD1 may provide an explanation for the higher levels of RASD1 observed in astrocytoma tissues of grade II and grade III." (PMID 28600528, 2017). "Interestingly, higher RASD1 levels predicted better survival in astrocytoma patients (n = 185, P = 0.086)." (PMID 28600528, 2017). "In addition, we found that high levels of RASD1 predicted good survival in astrocytoma patients." (PMID 28600528, 2017). "However, RASD1 gene expression showed no significant changes in grade II (n = 13), grade III (n = 16) or grade IV (n = 159) astrocytoma tissues compared to the nontumor group (n = 8) (all P > 0.05)." (PMID 28600528, 2017). "Interestingly, RASD1 protein levels were significantly higher in grade II and grade III astrocytoma tissues than in nontumorous brain tissues." (PMID 28600528, 2017).
lung adenocarcinoma (2 papers, 2017 to 2021). A carcinoma that arises from the lung and is characterized by the presence of malignant glandular epithelial cells. "Finally, Rasd1 has been reported to induce apoptosis when transfected into lung adenocarcinoma cells." (PMID 34625540, 2021).
steatosis (2 papers, 2021). Increased lipid within the cytoplasm of cells. "Eventually, we determined 10 hub genes (Down-regulated genes: MYC, TGFB3, ADAMTS1, THBS1, RASD1, PCDH20; Up-regulated genes: MAMDC4, CYP7A1, GINS2, and PDLIM3) related to NAS and steatosis." (PMID 34777484, 2021). "RTP3 in the yellow module was in high expression for steatosis and NASH samples, while RASD1 in the yellow module was in low expression for steatosis and NASH samples." (PMID 34041361, 2021).
Adrenocortical carcinoma (1 paper, 2025). "The expression of RASD1 inversely correlated to survival outcomes in Adrenocortical carcinoma (ACC), Bladder Urothelial Carcinoma (BLCA), and Mesothelioma (MESO)." (PMID 40362656, 2025).
allergic disease (1 paper, 2022). An immune response that occurs following re-exposure to an innocuous antigen, and that requires the presence of existing antibodies against that antigen. "Rasd1 was induced by dexamethasone which was commonly used as an anti-inflammatory glucocorticoid in various disorders including heart diseases, autoimmune diseases, and allergic diseases." (PMID 35938163, 2022).
anemia (1 paper, 2026). A reduction in the number of red blood cells, the amount of hemoglobin, and/or the volume of packed red blood cells. "Low RASD1 mRNA levels correlated significantly with advanced DS stage, anemia, hypercalcemia, and elevated M-protein concentrations (P < 0.05)." (PMID 41627676, 2026).
anxiety disorder (1 paper, 2024). A category of psychiatric disorders which are characterized by anxious feelings or fear often accompanied by physical symptoms associated with anxiety. "Rasd1, found predominantly in the brain, has played a crucial role in circadian control, metabolic diseases, neurotoxicity, and anxiety disorders." (PMID 37735980, 2024). "Rasd1 plays an essential role mainly in fat metabolism, the circadian clock, anxiety disorders, and neurotoxicity." (PMID 37735980, 2024).
B-cell acute lymphoblastic leukemia (1 paper, 2025). A neoplasm of lymphoblasts committed to the B-cell lineage, typically composed of small to medium-sized blast cells. "Conversely, prior studies have reported that elevated RASD1 expression correlates with poor survival and chemotherapy resistance in B-cell acute lymphoblastic leukemia (B-ALL)." (PMID 40362656, 2025).
B-cell neoplasm (1 paper, 2025). A group of heterogeneous lymphoid tumors generally expressing one or more B-cell antigens or representing malignant transformations of B-lymphocytes. "Patients with sarcoma, esophagogastric cancer, hepatobiliary cancer, and mature B-cell neoplasms exhibited the highest rate of gene alterations in RASD1 (>2%) when compared to other cancer types." (PMID 40362656, 2025).
brain cancer (1 paper, 2025). A primary or metastatic malignant neoplasm affecting the brain. "For example, there was variable RASD1 expression across different cancer cell lines, with particularly notable variability between brain cancer cell lines." (PMID 40362656, 2025).
brain glioma (1 paper, 2017). A malignant glioma that involves the brain. "In brain glioma, one study identified RASD1 as a significantly dysregulated gene in oligodendroglial tumors that responded to chemotherapy." (PMID 28600528, 2017).
cardiac hypertrophy (1 paper, 2024). "Therefore, the RASD1/NAMPT axis emerges as a crucial cellular signalling pathway implicated in the pathogenesis of cardiac hypertrophy." (PMID 39535387, 2024). "Therefore, it demonstrates that oxidative stress, energy synthesis, and disrupted autophagy balance in cardiomyocytes resulting from downregulation of the RASD1/NAMPT axis may underlie the increased cardiac hypertrophy and cardiovascular risk observed in female HCM patients." (PMID 39535387, 2024). "Accumulating evidence indicates a correlation between decreased RASD1 expression and the development of cardiac hypertrophy." (PMID 39535387, 2024). "Additionally, more pronounced cardiac hypertrophy was observed in SHR females, characterized by reduced left ventricular inner diameters, suggesting that RASD1/NAMPT axis is prabably a key mechanism." (PMID 39535387, 2024).
clear-cell renal-cell carcinoma (1 paper, 2024). "With the cluster analysis, it was possible to know the actions performed by the signature genes within the cellular environment of clear-cell renal-cell carcinoma and how the effects of this regulatory process occur, indicating new roles for the lncRNA AF117829.1 and the mRNA RASD1." (PMID 38673800, 2024).
corticotroph adenoma (1 paper, 2017). "The current case identifies a novel RASD1 mutation in a USP8-positive corticotroph adenoma." (PMID 28487882, 2017).
Dandy-Walker malformation (1 paper, 2016). "Furthermore, our data suggests the involvement of CNTN6 and KLHL15 in the etiology of agenesis of the corpus callosum, the involvement of RASD1 and PTPRD in Dandy-Walker malformation, and the involvement of ERMARD in ventriculomegaly." (PMID 27087860, 2016).
dilated cardiomyopathy (1 paper, 2019). Cardiomyopathy which is characterized by dilation and contractile dysfunction of the left and right ventricles. "RASD1 was found to be up-regulated in samples from patients with ischemic disease compared to patients with dilated cardiomyopathy (heart damage despite normal blood flow), and non-failing hearts." (PMID 30958265, 2019).
Ewing sarcoma (1 paper, 2022). A small round cell tumor that lacks morphologic, immunohistochemical, and electron microscopic evidence of neuroectodermal differentiation. "All these results showed that PHLDA1 and RASD1 (key DEeRNAs) were extensively expressed in cancer stem cells of Ewing sarcoma, which were potential targets for tumor treatment." (PMID 36092920, 2022).
Hypertension (1 paper, 2024). The presence of chronic increased pressure in the systemic arterial system. "Animal experiments confirmed reduced RASD1 and NAMPT expression in hypertrophic hearts from female SHRs with spontaneous hypertension." (PMID 39535387, 2024).
Merkel cell carcinoma (1 paper, 2025).
myocardial ischemia (1 paper, 2022). A disorder of cardiac function caused by insufficient blood flow to the muscle tissue of the heart. "Therefore, we cultured H9C2 cells in serum-free DMEM medium to mimic the state of nutrient loss after acute myocardial ischemia and to determine the expression of Rasd1 and Kmt2d in the H9C2 cells." (PMID 35938163, 2022). "Our current study suggested that the decrease of Rasd1 at its endogenous level in the condition of myocardial ischemia may worsen myocardial ischemic injury." (PMID 35938163, 2022). "Therefore, Rasd1 may be a potential anti-inflammatory therapeutic target, which could reduce the adverse effects of dexamethasone that is widely used clinically, especially when the patients have myocardial ischemia." (PMID 35938163, 2022). "Interestingly, the expression of Rasd1 was reduced after 3 h of serum deprivation in the H9C2, which was consistent with the downregulation of Rasd1 after myocardial ischemia in vivo." (PMID 35938163, 2022).
Obesity (1 paper, 2025). Accumulation of substantial excess body fat. "RASD1 is involved in various physiological processes: in neurons, it acts as a nitric oxide effector and inhibits the adaptor protein FE65-APP-mediated signaling; in mice, RASD1 knockout prevents diet-induced obesity." (PMID 40362656, 2025).
oligodendroglial tumor (1 paper, 2017). Oligodendrogliomas are cerebral tumors that are differentiated from other gliomas on the basis of their unique genetic characteristics and better response to chemotherapy. "A previous study identified that RASD1, a member of the RAS superfamily of small G-proteins, is a significantly dysregulated gene in oligodendroglial tumors that responded to chemotherapy." (PMID 28600528, 2017).
pituitary tumor (1 paper, 2020). A benign or malignant neoplasm affecting the pituitary gland. "RASD1 is a highly conserved member of the Ras family of monomeric G proteins that was initially identified as a dexamethasone-inducible gene in AtT-20 mouse pituitary tumor cells." (PMID 32318090, 2020).
sarcoma (1 paper, 2025). A usually aggressive malignant neoplasm of the soft tissue or bone. "In our analysis, we identified copy number variation as the most common genetic alteration of RASD1, particularly in sarcoma." (PMID 40362656, 2025).
subarachnoid hemorrhage (1 paper, 2024). A serious neurological disorder characterized by intracranial hemorrhage into the subarachnoid space. "Rasd1 has been reported to be correlated with neurotoxicity, metabolism, and rhythm, but its effect in case of subarachnoid hemorrhage (SAH) remained unclear." (PMID 37735980, 2024).
thymoma (1 paper, 2025). A neoplasm arising from the epithelial cells of the thymus. "Furthermore, RASD1 mRNA is generally downregulated in most cancers compared to normal tissue; however, it exhibits upregulation in thymoma (THYM) and uterine corpus endometrial carcinoma (UCEC)." (PMID 40362656, 2025).
cancer (30 papers, 2007 to 2025). A tumor composed of atypical neoplastic, often pleomorphic cells that invade other tissues. "The gene list was then passed through Enrichr to explore the functional associations and pathways linked to RASD1 expression in these cancer types." (PMID 40362656, 2025). "We investigated potential associations between RASD1 mRNA and protein expression levels, gene mutations, methylation patterns, overall cancer survival, immune cell infiltration in tumors, and pathway regulation across multiple cancers." (PMID 40362656, 2025). "The analysis of immune infiltration and enrichment of genes associated with RASD1 suggests potential mechanisms by which RASD1 could influence tumor immunity, genetic alterations, and signaling pathways in cancers." (PMID 40362656, 2025). "Therefore, we investigated the copy numbers and mutations of RASD1 across all cancers in the TCGA database to assess potential factors that could be influencing the regulation of RASD1 expression." (PMID 40362656, 2025). "Since cell lines are commonly used in cancer biology research to study molecular mechanisms and testing of therapeutic agents, we examined RASD1 expression in cancer cell lines." (PMID 40362656, 2025). "Here, we systematically analyzed RASD1 expression patterns in both tumor and normal tissues, utilizing publicly available datasets such as The Cancer Genome Atlas (TCGA), Genotype-Tissue Expression (GTEx), and The Human Protein Atlas." (PMID 40362656, 2025). "With growing interest in targeting metabolic pathways in RAS-driven cancers, RASD1 presents a promising candidate for therapeutic intervention, either independently or in combination with existing metabolic or apoptotic strategies." (PMID 40362656, 2025). "Our analysis revealed a significant downregulation of RASD1 mRNA expression in several cancer types compared to normal tissues, correlating with low levels of promoter methylation." (PMID 40362656, 2025). "While our analysis showed that RASD1 mRNA downregulation is a common feature in multiple cancers including KIRC, ACC, and BLCA, its prognostic implications are not the same." (PMID 40362656, 2025). "Despite these findings, there remains a need for a comprehensive exploration of RASD1′s role across various cancer types to fully understand its potential role in cancer." (PMID 40362656, 2025). "Although we observed lower levels of promoter methylation of RASD1 in cancer compared to normal tissues, the expression of RASD1 increases in ESCA, HNSC, PRAD, THCA, and UCEC." (PMID 40362656, 2025). "The varied expression patterns of RASD1 across different cancer types suggest a potential role in patient outcomes." (PMID 40362656, 2025). "Subsequent experimental work is needed to unravel the precise role of RASD1 in the complex landscape of cancer development and patient survival across cancers." (PMID 40362656, 2025). "The discrepancies between RASD1 mRNA and protein levels across various tissues and cancer types suggest complex post-transcriptional and post-translational regulations." (PMID 40362656, 2025). "In this Pan-cancer analysis study, we observed distinct expression patterns of RASD1 across different tissues and cell types." (PMID 40362656, 2025). "In conclusion, RASD1 is commonly expressed in various tissues and exhibits lower expression in most cancer types, often related to poor clinical outcomes." (PMID 40362656, 2025). "To further investigate the cancer-specific role of RASD1, we extended our analysis to ACC, BLCA, and MESO, in which RASD1 expression was inversely correlated with patient survival, using the same algorithms." (PMID 40362656, 2025). "Immune cell infiltration analysis indicated that elevated RASD1 expression is associated with an increased infiltration of CD4+ T cells and myeloid-derived dendritic cells in cancer." (PMID 40362656, 2025).
cancer (continued). "Despite these limitations, the study offers valuable insights into RASD1′s potential role in cancer and highlights the need for focused experimental investigations to unravel its precise functions and therapeutic implications." (PMID 40362656, 2025). "Here, we investigated RASD1 expression across multiple tissues and cancers, utilizing data from The Cancer Genome Atlas (TCGA), Human Protein Atlas, and Genotype-Tissue Expression (GTEx) databases." (PMID 40362656, 2025). "Previous studies have highlighted the various roles of RASD1 in multiple cancer types, functioning as both a tumor suppressor and an oncogenic regulator." (PMID 40362656, 2025). "Based on Oncomine database, we identified that expression of CCR1, CD3D, MAZ, PHLDA1, and RASD1 was higher in tumor than that in normal tissue at the pan-cancer level." (PMID 36092920, 2022). "On the other hand, RASD1 is a Ras-related small G protein that inhibits cell proliferation in multiple cell lines from different types of cancers." (PMID 34830961, 2021). "Among these altered genes, RASD1 has been identified as a novel tumor suppressor that regulates the proliferation, apoptosis, and metastasis of cancer cells." (PMID 32651355, 2020). "Notably, RASD1 expression is lower in cancer tissue than in normal tissue in KIRC, and its protein expression is low in LGG and PAAD." (PMID 40362656, 2025). "To explore the potential tumor suppressive mechanisms of RASD1 in KIRC, LGG, and PAAD, we used GEPIA2 to identify the top 50 genes with similar expression patterns as RASD1 in these three cancers for which high RASD1 expression correlated with better survival outcomes." (PMID 40362656, 2025). "In our study, we observed relatively low promoter methylation of RASD1 in cancer tissues compared to normal tissues, suggesting that RASD1 may function as a tumor suppressor gene." (PMID 40362656, 2025). "However, this study highlights the need for further exploration to elucidate the specific molecular mechanisms RASD1 influences in different cancer contexts." (PMID 40362656, 2025). "Thus, while a general correlation exists between lower promoter methylation and gene expression, our findings suggest a complex regulation of RASD1 in cancer and only partially explains the range in RASD1 expression across cancer types." (PMID 40362656, 2025). "Furthermore, RASD1 expression can be induced by dexamethasone, a common steroid used in cancer patients that can reduce inflammation." (PMID 40362656, 2025). "Our enrichment analyses highlight potential mechanisms of how high RASD1 expression may negatively regulate cancers such as KIRC, LGG, and PAAD." (PMID 40362656, 2025). "We found minimal genetic alterations in RASD1; however, the promoter methylation levels of RASD1 are lower in several cancer types, suggesting that low promoter methylation might predominantly regulate its expression in cancer." (PMID 40362656, 2025). "However, the role of RASD1 expression in cancer remains relatively unexplored, with limited in vitro studies suggesting its potential anti-tumor effects." (PMID 40362656, 2025). "Therefore, we examined if there was a correlation between RASD1 expression levels and the overall survival of cancer patients." (PMID 40362656, 2025). "While RASD1 expression generally remains low in most cancers compared to normal tissues, we observed the opposite in THYM, a cancer with a low incidence of KRAS mutations, and UCEC, a cancer in which patients with KRAS mutations exhibit a more favorable prognosis." (PMID 40362656, 2025). "Moreover, RASD1 RNA expression was consistently lower in cancer tissues compared to normal tissues across several malignancies, except in THYN and UCEC, where it was upregulated." (PMID 40362656, 2025).